EXD1 (exonuclease 3'-5' domain containing 1)
Description:
RNA-binding component of the PET complex, a multiprotein complex required for the processing of piRNAs during spermatogenesis. The piRNA metabolic process mediates the repression of transposable elements during meiosis by forming complexes composed of piRNAs and Piwi proteins and governs the methylation and subsequent repression of transposable elements, preventing their mobilization, which is essential for the germline integrity (By similarity). The PET complex is required during the secondary piRNAs metabolic process for the PIWIL2 slicing-triggered loading of PIWIL4 piRNAs. In the PET complex, EXD1 probably acts as an RNA adapter. EXD1 is an inactive exonuclease (By similarity).
Synonyms: EXDL1; MGC33637
Tractability: PROTAC: ubiquitination databases record sites on it.
Gene: Protein-coding gene on chromosome 15 (41,182,725 to 41,230,757, reverse strand). Ensembl gene ENSG00000178997.
Subcellular location: Cytoplasm
Gene Ontology:
Molecular function: protein binding; 3'-5' exonuclease activity; protein homodimerization activity; RNA binding; nucleic acid binding
Biological process: piRNA processing; regulatory ncRNA-mediated gene silencing
Cellular component: cytoplasm; P granule; PET complex
Genetic constraint (gnomAD): Loss-of-function variants: 64 observed, 51.31 expected, observed/expected ratio (o/e) 1.25, 90% interval 1.02 to 1.54. The upper end of that interval is the gene's LOEUF score, 1.54, which puts it in group 6 of 6, group 1 being the genes least tolerant of losing a copy. Missense variants: 747 observed, 698.03 expected, observed/expected ratio (o/e) 1.07, 90% interval 1.01 to 1.14. Synonymous variants: 234 observed, 253.59 expected, observed/expected ratio (o/e) 0.92, 90% interval 0.83 to 1.03.
Homologues: Orthologues: chimpanzee EXD1 (99% identical), macaque EXD1 (95% identical), pig EXD1 (82% identical), dog EXD1 (80% identical), rabbit EXD1 (76% identical), guinea pig EXD1 (74% identical), mouse Exd1 (73% identical), rat Exd1 (72% identical), tropical clawed frog exd1 (37% identical), zebrafish exd1 (22% identical), Drosophila melanogaster egl (19% identical), Caenorhabditis elegans egal-1 (15% identical). Paralogues in human: EXOSC10 (15% identical).